CD4 (CD4 molecule)
Diseases named in the same sentence as CD4 in open-access papers (continued):
Sharing a sentence is not in itself a finding about the gene and the disease.
tumor (continued). "Notably, Clod treatment led to no obvious changes in infiltration of CD8+ or CD4+ T cells, suggesting that KC clearance had no direct effect on T cell-mediated anti-tumor immunity." (PMID 40796724, 2025). "Interestingly, BPO-derived tumor cell lines engrafted subcutaneously develop tumors that generally contain a greater CD8/CD4 T cell ratio (data not shown), compared to autochthonous BPO tumors." (PMID 41279375, 2025). "CD4+ T cells are pivotal for orchestrating adaptive immunity, and their low infiltration in the context of high NTRK3 expression may suggest an immunosuppressive microenvironment that favors tumor progression." (PMID 40142285, 2025). "We evaluated tumor specific MHC-I (tsMHC-I), tsMHC-II positive proportion of all the detected tumor cells in each patient, and the proportion of CD4 + and CD8 + T cell infiltration in each patient using multiplex immunohistochemistry (mIHC) (PanCK, HLA-A, HLA-DR, CD4, CD8, and DAPI)." (PMID 40495188, 2025). "Notably, in CT26-ULBP2 tumor-bearing mice, CD4+ T cell depletion did not significantly reduce tumor volume or weight on day 21 post-transplantation compared to isotype control antibody, and no complete regressions were observed." (PMID 40558520, 2025). "Moreover, the depletion of CD4+ CD25+ FoxP3 Tregs improves the efficacy cancer immunotherapies, such as checkpoint inhibitors, enhances the immune response and prolongs the survival of tumor patients." (PMID 40216744, 2025). "The UA technique is based on ultrasonic waves that generate energy to fragment and aspirate the tumor tissue, and here we show that this mechanical stress does not induce differential expression of the tested markers on CD4+ or CD8+ T cells compared to tissues obtained via traditional resection." (PMID 40002198, 2025). "Moreover, activin A concentration‐dependently amplified the amount of CD4+ T cells in the tumor, without significantly affecting NK cells." (PMID 39727149, 2025). "Notably, while high densities of CD4+ T cells, CD8+ T cells, and CD56+ NK cells are positively correlated with higher tumor regression rates, the interplay of immunosuppressive factors may partially diminish the statistical significance of this effect." (PMID 40936903, 2025). "Furthermore, after characterising tumour infiltrating lymphocytes (TILs) in PDAC, we see that even though there is limited exhaustion in a subset of CD8 T cells, we observed that a significant number of CD4 and CD8 T cells were senescent." (PMID 39915477, 2025). "We previously reported that CD4+ T cell depletion significantly suppresses tumor growth in syngeneic mice bearing B16F10-mock tumors; however, it remained to be clarified whether CD4+ T cell depletion could suppress tumor growth under NK cell-depleted conditions." (PMID 40558520, 2025). "Moreover, ascites-derived CD4+ T cells and CD8+ T cells exhibited significantly reduced proportions of CD28, with 63.60 ± 10.77% of CD4+ T cells and 16.05 ± 5.57% of CD8+ T cells, compared to PB and tumor samples." (PMID 41221283, 2025). "Given that tumor-infiltrating CD4+ and CD8+ T cells may arise from naïve, central memory, or effector memory precursor cells, we analyzed CD4+ and CD8+ T cells from the spleen, TDLNs, and tumors of mice receiving the 3 types of therapy and compared the results with untreated controls." (PMID 40813233, 2025). "Here, fine tuning of CD4+:CD8+ T cell ratio without impacting anti-tumor immunity is required." (PMID 39893177, 2025). "EGFR and IDH1 were highly expressed in tumor cells, FAP and COL1A1 were confined to fibroblasts, CD68 and ITGAM marked macrophages, PECAM1 and CDH5 identified endothelial cells, OLIG2 and MOG were specific to oligodendrocytes, while CD4 and CD3D defined T-cell subsets." (PMID 41208987, 2025). "This decreased population of activated CD4+ T cells upon IMDQ-PEG-cholesteryl treatment might explain the previously observed lack of protection against a challenge tumor." (PMID 40230629, 2025).
tumor (continued). "Although we have not directly assessed the efficacy of immunotherapy in this context, our findings indicate a relationship between tumor POPDC3 expression, PD-1-positive CD4+ T cell infiltration, and potential T cell exhaustion, which could inform future studies on immunotherapy responsiveness." (PMID 39971925, 2025). "Similarly, anti-IL-1β treatment increased the infiltration of CD8 + and CD4 + T cells in the KPC-3403 tumor compared to the control sample; and no significant DEGs were identified in the control versus anti-IL-1β treated samples." (PMID 39948655, 2025). "Therefore, we hypothesize that ASCC3 exerts its antitumor immune effects and provides protective effects primarily by coordinating the immune roles of different types of CD4+ T cells, CD8+ T cells, M2 macrophages, and Tregs in the tumor microenvironment." (PMID 40881169, 2025). "Tumor cells within these immune-enriched neighborhoods demonstrated PD-L1 positivity, and within the tumor area, we observed frequent interactions between PD-1+ T cells and PD-L1+ cells, as well as ICOS+ CD4+ T cells, indicating a more active, tumor-reactive phenotype." (PMID 41254766, 2025). "Unlike the pancreatic model that relies on nonspecific tumor markers, our approach incorporates HIV-specific immunological parameters including CD3+ and CD4+ T cell counts, which directly reflect the underlying pathophysiological mechanisms of lymphomagenesis in immunodeficient hosts." (PMID 40989183, 2025). "However, the depletion of NK cells, CD4+ T cells, or CD8+ T cells all led to an augmented incidence of lung metastasis, signifying that these cells assume significant roles in control of tumor lung metastasis." (PMID 40135850, 2025). "However, depletion of CD4+ T cells (purple) in 4T1‐sh‐mR1#1 tumor did not significantly alter tumor growth." (PMID 39932384, 2025). "Finally, while CD4+ and CD8+ effector-memory populations were enriched in both tumor and peripheral compartments, their functional impact on tumor immunity and systemic surveillance remains to be fully elucidated, underscoring the need to dissect tumor-peripheral immune crosstalk." (PMID 41253784, 2025). "However, TIM-1+B cells in the tumor were not related to the density of CD4+ T cells in the tumor (p = 0.0924, r = 0.1506, 95% CI −0.0302 to 0.3218)." (PMID 40519901, 2025). "Tumor-resident CD8+ T cells, polarized by such a type 1 cytokine–rich environment, downregulate tumor-specific immune responses by facilitating the local migration of CD4+Foxp3+ Tregs through the accumulation of several CCR5-specific cytokines, such as MIP-1α (CCL3) and MIP-1β (CCL4)." (PMID 40553564, 2025). "In contrast, the enrichment of CD8+ and CD4+ memory T cells and DCs in non-metastasis samples indicates that effective anti-tumor immune surveillance may play a critical role in restraining metastasis." (PMID 41373733, 2025). "Our results also suggest that the CD4+ T-cell-mediated anti-tumor response may not substantially require FasL and GzmB expression." (PMID 39885128, 2025). "While both CD4+ and CD8+ T cells are activated by the treatment, only CD8+ T cells are required to achieve TA-expressing cancer cell clearance, confirming that, when TA and cytokines are co-delivered, robust anti-tumor immunity is achieved independently of CD4+ T cell help." (PMID 40216735, 2025). "Moreover, CD4+ and CD8+ T-cells decreased in the Plk3-overexpressing tumor model." (PMID 39866232, 2025). "Moreover, the levels of CD3+, CD4+, CD8+, and PD-1+ lymphocytes in ascitic fluid were substantially higher than the corresponding TILs in primary tumor tissue from our previous study, with values exceeding 40% for all markers except PD-1+, for which the value was around 20%." (PMID 40723153, 2025). "However, the current study revealed that knockdown of RNase1 in 4T1 cells decreased tumor growth and did not affect CD4+ T‐cell activity in vivo." (PMID 39932384, 2025).
tumor (continued). "However, the fundamental question of how tumor-specific memory CD4+ T cells arise in the absence of necessary priming signals remains unresolved." (PMID 40279312, 2025). "Notably, the large interpatient variability in CD4/CD8 ratios and NK cell frequencies underscores the complexity of tumor–immune interactions, which may differ by cancer subtype, disease stage, and individual host factors." (PMID 40282458, 2025). "Interestingly, CD4+ Tconv poorly expressed Tbet in TDLNs, whereas CD4+ Tconv co-expressing ICOS and Tbet were observed in tumors, suggesting that full engagement of the Th1 program occurs in the tumor microenvironment." (PMID 40460830, 2025). "In our study, tumor tissues with high CXCR2P1 expression exhibited significantly higher proportions of activated CD4+ T cells and TFH cells compared to low CXCR2P1 expression tumor, suggesting that the tumor tissues with high CXCR2P1 expression may have higher immunogenicity." (PMID 40176817, 2025). "In contrast, CD4 + T cells contribute to long-term persistence and cytokine secretion but may not be as effective in direct tumour lysis ​." (PMID 40624498, 2025). "EDB-FN expression and the infiltration of CD4+ and CD8+ T lymphocytes in the tumors were determined by immunohistochemistry (IHC) and immunofluorescence (IF) staining, respectively, and correlated with MRMI observations, tumor response, and therapeutic outcomes." (PMID 41041061, 2025). "Overall, GZMB+ cells comprised the majority (~50%) of circulating CD4+ cells with tumor-matched TCRs, and GZMB+ and GZMK+ cells together represented more than 40% of intratumoral CD4+ cells with blood-matched TCRs despite these cells constituting the minority of total CD4+ cells." (PMID 40299576, 2025). "However, tumour‐bearing mice that received 3 weeks of chronic restraint stress (CRSTumor) displayed an average CD4+/CD8+ ratio of 2.4 ± 0.2, which was similar to control animals (1.8 ± 0.1) and to stressed mice in which tumours spontaneously regressed (2.1 ± 0.5; CRSRegress)." (PMID 40172096, 2025). "In a pancreatic ductal adenocarcinoma (PDAC) mouse model, endogenous bacterial ablation not only promoted the differentiation of CD4+ T cells into Th1 cells and CD8+ T-cell activation but also up-regulated PD-1 expression, thereby increasing the efficacy of immunotherapy and preventing tumor growth." (PMID 40556945, 2025). "In general, the high number of the CD4+ and CD8+ T cells in tumor stroma indicates a better prognosis; however, the presence of high numbers of CD8+ T cells in NSCLC patients after resection could be considered as the additional factor in the classification involving tumor-node-metastasis." (PMID 40136652, 2025). "Although vaccine delivery using the Oligomer scaffold elicited significantly higher antibody responses and IFNγ+CD4+ T cells, a limitation of this study is the lack of direct evidence demonstrating the effectiveness of these responses against viral or tumor challenges." (PMID 41295519, 2025). "Gopalakrishnan and colleagues demonstrated that transferring stool from anti-PD-1 nonresponders expands the number of tumor-infiltrating RORγt+ Th17 cells and splenic CD4+IL-17+ Tregs in recipient mice, indicating that the gut microbiota drives immunosuppression in a Th17-dependent manner." (PMID 40770084, 2025). "Additionally, two patients exhibited CD4+ T cell reactivity against non-vaccine neoantigens, accompanied by tumor-infiltrating neoantigen-specific T cell clonal." (PMID 40661781, 2025). "In the tumor immune microenvironment, CD4+ T cells can stimulate and maintain the differentiation of macrophages, CD8+ T cells and NK cells by secreting cytokines such as IFN-γ, TNF and IL-2, and inhibit angiogenesis of tumor, thus playing an anti-tumor effect." (PMID 40176817, 2025).
tumor (continued). "Furthermore, cilengitide, WP1066, or AR-A014418 treatment increased activated CD4+ (CD45+CD3+CD8–CD4+CD69+) and CD8+ T cells (CD45+CD3+CD8+CD4–CD69+), and these effects were improved when CT2A tumor–bearing mice received the treatment with cilengitide combined with WP1066 or AR-A014418." (PMID 40131864, 2025). "Interestingly, both hCD4+ and hCD8+ T cells were isolated from the primary tumor sites, with CD4/CD8 average ratios of 0.9732 (responders) and 1.859 (non-responders)." (PMID 40896578, 2025). "Additionally, this study did not assess the effects of IL-2 or its receptor blockade, nor did it examine CD4+ T cell depletion using in vivo tumor models." (PMID 40343532, 2025). "Furthermore, activin A augmented CD4+ T cell abundance within the tumor but had no influence on NK cell count." (PMID 39727149, 2025). "Moreover, the frequencies of CD8+ and CD4 + T cells, and the relative abundance of naïve T cells (CD44-CD52L+), effector/memory T cells (CD44+CD62L−), and central memory T cells (CD44+CD62L+) cells was unaffected in the tumor-draining lymph nodes." (PMID 40796746, 2025). "Another entity that may involve the skin is intravascular cutaneous ALCL, with anaplastic tumor cells expressing CD4 and CD30, while are negative for EBER." (PMID 40565334, 2025). "While this effect was not statistically significant, it supports the idea that NK cells may play a limited role in tumour control in IL17A‐proficient contexts, in line with our previous findings that CD4+ T cells are the predominant effectors in these settings." (PMID 40831074, 2025). "In this synergistic setting, the frequency of IFN-γ+ and TNF-α+ CD4+ T cells in the SFB+ B16-3340 group showed extremely strong negative correlations with tumor burden (r = -0.9057 and r = -0.9742, respectively), indicating a direct linear relationship between Th1 responses and tumor eradication." (PMID 41441899, 2025). "Thus, CBD in the tumor microenvironment may promote direct activation of CD4+T cells and CD8+T cells and their interaction between immune cells and tumor cells." (PMID 40475776, 2025). "Moreover, aspirin treatment in vivo resulted in increased capacity for TCR-driven S6 phosphorylation among antigen-experienced CD4+ and CD8+ T cells from tumour-bearing lungs of wild-type mice, to increased levels observed in Arhgef1-deficient mice treated with either aspirin or vehicle control." (PMID 40044852, 2025). "Flow cytometry analyzing the proportion of CD3+, CD4+ and CD8+ T cells in tumor tissue further confirmed that αMSLN treatment could significantly enhance the infiltration of CD3+CD8+ T cells (p = 0.0011) but not the CD3+CD4+ T cells." (PMID 39887656, 2025). "Thus, it could stabilize the interaction between CD4+ T cells and MHC-II+ tumor cells which is important in immunotherapy." (PMID 41425696, 2025). "Such functions, however, might not be equivalent in lymphomas, where tumor cells are antigen‐presenting cells that benefit from CD4 TH‐secreted cytokines." (PMID 40571973, 2025). "The ligation of CD40 expressed by cDC1 during CD4+ T‐cell priming is critical for robust licensing of cDC1s; without this interaction, tumor rejection mediated by CD8+ T cells may fail." (PMID 40667699, 2025). "To determine whether loss of CD4+ and/or CD8+ T cells is necessary for RCOR2-mediated tumor growth, we administered anti-CD4 antibody, anti-CD8 antibody, anti-CD4/CD8 antibodies or control antibody isotype intraperitoneally into tumor-bearing mice to deplete CD4+ and CD8+ T cells." (PMID 40608411, 2025). "The decline in CD4+ T cells in non-treated tumor-bearing dogs, further exacerbated by corticosteroid treatment, suggests impaired adaptive immunity, that could weaken antitumor responses." (PMID 40342421, 2025). "Thus, 40% of CD8-positive patients (n = 10) and 56.82% of CD4-negative patients (n = 25) had tumor margin infiltration." (PMID 40362599, 2025).
tumor (continued). "The results showed a significant reduction in the CD4+CD25+ population but no change in the CD8+CD25+ population among splenic T cells co-cultured with DC2.4 cells previously exposed to EO771 tumor antigens in the presence of ADMA." (PMID 40429627, 2025). "Importantly, BDCA‐1+ cDC2 levels may predict responses to PD‐1 blockade therapy, even in tumors with low BDCA‐3+ cDC1 content, particularly when tumor cells express MHCII and engage CD4+ T cells." (PMID 40667699, 2025). "Promote the infiltration of CD4+ and CD8+T cells into the tumor microenvironment, and at the same time reverse the resistance of B16 melanoma to anti-PD-1 treatment alone, enabling the combined treatment to significantly inhibit tumor growth and prolong the survival period of mice." (PMID 41335282, 2025). "Conversely, cluster of differentiation 4 (CD4)+Foxp3+ regulatory T cells (Tregs) act as immunosuppressors in antitumor immunity, typically accumulating in the TME of CRC patients and entering peripheral blood as the tumor progresses, inducing immune tolerance and promoting immune evasion." (PMID 40255905, 2025). "In addition to the potential tumor killing by CD4+ T cells, our study does not rule out the possible contribution of other mechanisms to the M002-mediated anti-GBM effects." (PMID 39885128, 2025). "The elevated levels of both CD4+ and CD8+ T cells in the low‐mPCDS group suggest that these patients benefit from a well‐orchestrated immune surveillance system, which may help in controlling tumour growth more effectively." (PMID 39828988, 2025). "Moreover, in vivo experiments using a B16F10 mouse melanoma model demonstrated that injection of pDox + RA@adipocytes significantly delayed tumor growth, accompanied by increased infiltration of CD4+ and CD8+ T cells into the tumor tissue and a reduction in the number of Tregs." (PMID 41345744, 2025). "PD-1 inhibitors restore the ability of immune cells, such as CD4 + T cells, CD8 + T cells, and natural killer cells, to recognize and kill tumor cells by blocking the binding of PD-1 to the membrane of immune cells and PD-L1 expressed on the membrane of tumor cells." (PMID 40606464, 2025). "Furthermore, triple therapy treated mice had an increased percentage of central memory and effector memory CD8 T cells in the tumor microenvironment and increased CD8+ T effector memory and CD4 central memory T cells in spleen compared with radio-immunotherapy." (PMID 40139833, 2025). "Although a modest decrease in the absolute number of CD4+ T cells per mg tumor was observed at this timepoint (407.9 ± 34.3 vs. 190.9 ± 58.3; P = 0.024), we observed no changes in the absolute number of CD8+ T cells, Tregs, or neoantigen-specific CD8+ T cells per mg tumor." (PMID 39881590, 2025). "The levels of tumor-infiltrating CD4+CD25+Foxp3+ Treg cells were not affected by p38 blockade." (PMID 41282257, 2025). "In addition, clinical IHC analysis of OPT5 showed substantial CD8+ T-cell presence and moderate CD4+ T-helper cells in the perivascular area of the tumor, as well as CD3+ T-cells throughout the tumor (data not shown)." (PMID 41331048, 2025). "Compared to the oe‐NC group, the number of CD4+ T cells and CD8+ T cells was significantly increased in the tumor tissues of mice in the oe‐NC+M2pep‐Cs NPs/Plerixafor group; while, these numbers were significantly decreased in the tumor tissues of mice in the oe‐CXCR4 group." (PMID 40536774, 2025). "Notably, the log odds ratio (LOD) of genus-level enrichment was nearly twofold higher in Rs, and this increase correlated with favorable features of the tumor immune microenvironment, including higher frequencies of CD8+ and CD4+ TILs, lower densities of CD68+ TAMs, and improved PFS." (PMID 41463268, 2025). "Conversely, ICIs failed to induce tumor regression in CD4+ T cell-depleted mice." (PMID 40191187, 2025).